DNAJC4 (DnaJ heat shock protein family (Hsp40) member C4)
Synonyms: HSPF2; MCG18; DANJC4
Tractability: Antibody: UniProt predicts a signal peptide or a membrane-spanning region.
Gene: Protein-coding gene on chromosome 11 (64,230,158 to 64,234,286, forward strand). Ensembl gene ENSG00000110011.
Subcellular location: Membrane
Gene Ontology:
Molecular function: protein binding
Biological process: protein folding; response to unfolded protein
Cellular component: membrane
Genetic constraint (gnomAD): Loss-of-function variants: 26 observed, 24.97 expected, observed/expected ratio (o/e) 1.04, 90% interval 0.76 to 1.44. The upper end of that interval is the gene's LOEUF score, 1.44, which puts it in group 5 of 6, group 1 being the genes least tolerant of losing a copy. Missense variants: 342 observed, 311.66 expected, observed/expected ratio (o/e) 1.1, 90% interval 1 to 1.2. Synonymous variants: 134 observed, 120.93 expected, observed/expected ratio (o/e) 1.11, 90% interval 0.96 to 1.28.
Homologues: Orthologues: chimpanzee DNAJC4 (86% identical), macaque DNAJC4 (72% identical), dog DNAJC4 (71% identical), pig DNAJC4 (69% identical), guinea pig DNAJC4 (68% identical), rat Dnajc4 (68% identical), mouse Dnajc4 (67% identical), zebrafish dnajc4 (40% identical), tropical clawed frog dnajc4 (34% identical), Caenorhabditis elegans dnj-8 (15% identical), Drosophila melanogaster CG10565 (15% identical), Drosophila melanogaster l(3)80Fg (15% identical), and 6 more. Paralogues in human: DNAJC13 (26% identical), DNAJC10 (20% identical), DNAJC11 (19% identical), DNAJC21 (18% identical), DNAJC1 (17% identical), DNAJC14 (16% identical), DNAJC7 (16% identical), DNAJC16 (15% identical), DNAJC25 (15% identical), DNAJC5B (15% identical), DNAJC9 (15% identical), DNAJC2 (15% identical), and 8 more.
Diseases named in the same sentence as DNAJC4 in open-access papers:
DNAJC4 is named in the same sentence as 10 diseases in open-access papers, as found by Europe PMC text mining. Sharing a sentence is not in itself a finding about the gene and the disease. The quoted sentences say what the papers report.
COVID-19 (1 paper, 2023). A disease caused by infection with severe acute respiratory syndrome coronavirus 2. "Therefore, we hypothesize that DNAJC4 may be an important biological target for glucocorticoids in the treatment of COVID-19 and its complications." (PMID 37426635, 2023). "First, we compared the expression levels of five genes in COVID-19 and controls, finding that the expression of BIRC5, DTL, and NDC80 increased in COVID-19 while DNAJC4 and LILRB2 decreased." (PMID 37426635, 2023).
infertile (1 paper, 2023). "Decreased Dnajc4 mRNA expression levels were found in spermatozoa from infertile men compared with those from fertile men." (PMID 37004113, 2023).
DNAJC4 also shares sentences with these, for which no sentence is quoted: breast carcinoma (1 paper); chronic myeloid leukemia (1); colorectal cancer (1); hematologic disorder (1); lung (1); lung adenocarcinoma (1); melanoma (1); ovarian carcinoma (1).